NDRG2 (NDRG family member 2)
Diseases named in the same sentence as NDRG2 in open-access papers (continued):
Sharing a sentence is not in itself a finding about the gene and the disease.
breast carcinoma (continued). "To determine the effect of NDRG2 overexpression on glucose deprivation-induced cell death, we first established stable clones of MDA-MB-231 breast cancer cells following transfection with the pCMV-Taq-2B (mock) or pCMV-Taq-2B-NDRG2 (NDRG2) plasmids." (PMID 25061501, 2014). "In this study, we examined the effect of NDRG2 expression on cell viability in MDA-MB-231 human breast cancer cells under conditions that are similar to the microenvironment of solid tumors, which include glucose deprivation." (PMID 25061501, 2014). "To investigate the effect of NDRG2 on breast cancer cell proliferation in high-glucose (25 mM) or low-glucose (5.5 mM) medium, we designed the following assays." (PMID 24636131, 2014). "Positive staining of anti-NDRG2 was found predominantly in the cytoplasm of both normal breast cells and breast cancer cells, but weaker staining for NDRG2 was observed in the cancer specimens compared with normal tissues." (PMID 24636131, 2014). "Breast cancer patients with high NDRG2 expression had longer overall survival than patients with low NDRG2 expression P = 0.0007 by logrank test)." (PMID 24636131, 2014). "We also found that NDRG2 adenovirus can be used to treat breast cancer by inhibiting cellular glucose uptake in a nude mouse xenograft model." (PMID 24636131, 2014). "We also found that breast cancer patients with high NDRG2 expression had longer disease-free survival and better overall survival compared with patients with low NDRG2 expression." (PMID 24636131, 2014). "To assess the significance of NDRG2 protein expression in the development and progression of breast cancer, we compared the histopathological characteristics of 269 breast cancer samples with available NDRG2 protein status." (PMID 24636131, 2014). "We have further demonstrated that NDRG2 plays an important role in tumour cell glucose transport, during which NDRG2 promotes the degradation GLUT1 protein to suppress glucose uptake in breast cancer cells in vivo and in vitro." (PMID 24636131, 2014). "Recently, it has been shown that breast cancer cells have low or undetectable NDRG2 expression, compared with high levels in normal tissues." (PMID 23800335, 2013). "We had reported that N-myc downstream–regulated gene (NDRG2) regulates colorectal cancer, breast cancer, clear cell renal cell carcinoma, pancreatic cancer, thyroid cancer and esophageal squamous cell proliferation, development, and apoptosis." (PMID 23307246, 2013). "Further studies have found that NDRG2 inhibits the proliferation, adhesion and invasion of breast cancer cells." (PMID 23800335, 2013). "Earlier studies have shown that NDRG2, a new tumour suppressor gene, is lowly expressed and correlates with the progression of breast cancer." (PMID 23800335, 2013). "In summary, we have demonstrated that NDRG2 mRNA levels are significantly reduced in thyroid and breast cancer, and that NDRG2 mRNA levels will be interesting to quantify in cervix and testis cancer." (PMID 21226903, 2011). "Differences at the mRNA level for NDRG2 are likely to be reflected at the protein level and our results are in agreement with other studies showing that NDRG2 protein is reduced in breast cancer." (PMID 21226903, 2011). "Using quantitative RT-PCR, we observed a significant reduction in the level of NDRG2 mRNA in a distinct set of tumor samples from both thyroid gland cancer (p = 0.02) and breast cancer (p = 0.004), compared with normal tissue." (PMID 21226903, 2011). "This is also similar with up regulation of NDRG2 induced morphological changes in malignant breast cancer cells." (PMID 22043305, 2011). "In conclusion, NDRG2 mRNA levels were significantly decreased in tumor samples from both thyroid and breast cancer, compared to normal tissue." (PMID 21226903, 2011).
breast carcinoma (continued). "The aim of this study was to examine levels of NDRG2 mRNA in several human cancers, with focus on breast cancer, by examining affected and normal tissue." (PMID 21226903, 2011). "Quantification of NDRG2 mRNA in breast cancer tissue showed a clear reduction in the level of NDRG2 mRNA in tumors compared to normal tissue." (PMID 21226903, 2011). "To elaborate on some of the data obtained from the CPA, we decided to quantify NDRG2 mRNA in sample sets obtained from patients diagnosed with thyroid gland cancer and breast cancer." (PMID 21226903, 2011). "Using quantitative RT-PCR, we have verified a reduction in thyroid cancer and shown, for the first time, that NDRG2 mRNA is statistically significantly down-regulated in breast cancer." (PMID 21226903, 2011). "Using quantitative RT-PCR, we demonstrated that NDRG2 mRNA levels were statistically significantly reduced in breast cancer tissue when compared to normal tissue." (PMID 21226903, 2011). "By quantifying the level of NDRG2 mRNA in 35 breast cancer samples, we observed a statistically significant down-regulation of NDRG2 in tumor samples compared to normal tissue." (PMID 21226903, 2011). "Other groups of researchers also described decreased expression of NDRG2 gene in tissues from various malignant neoplasms, e.g., in breast cancer, liver carcinoma, clear cell renal carcinoma and skin carcinoma." (PMID 20804549, 2010). "Interestingly, this group have found further differences in the expression and methylation patterns of NDRG2 between basal and luminal breast cancers, with the NDRG2 tumors having lower methylation and increased expression compared to the luminal tumors." (PMID 38611020, 2024). "On the other hand, another group have found NDRG2 to have a pro-oncogenic role in breast cancer; breast tumor samples had lower expressions of NDRG2 than normal breast tissue, and basal-like tumors had higher NDRG2 expression levels compared with luminal tumors." (PMID 38611020, 2024). "In addition, the heatmap expression data from breast cancer patient biopsies showed that most of the NDRG2 and EHF expression levels were positively correlated." (PMID 37958443, 2023). "MiR-181a-5p serves as an oncomiR and NDRG2 acts as a tumor suppressor in breast cancer." (PMID 34951340, 2022). "We aimed to investigate the role of miR-181a-5p and NDRG2 in breast cancer." (PMID 34951340, 2022). "MiR-181a-5p facilitates the progression of breast cancer via targeting NDRG2." (PMID 34951340, 2022). "The knockout of NDRG2 facilitated the proliferation, invasion, and glycolysis of breast cancer." (PMID 34951340, 2022). "We found upregulated miR-181a-5p and downregulated NDRG2 in breast cancer." (PMID 34951340, 2022). "In conclusion, miR-181a-5p facilitated tumor progression through NDRG2-induced activation of PTEN/AKT signaling pathway of breast cancer, suggesting that focusing on miR-181a-5p may provide new insight for breast cancer therapy." (PMID 34951340, 2022). "Additionally, NDRG2 levels were decreased in some breast cancer cells but increased in BT-474, HCC1569, HCC2157, and T47D cell lines." (PMID 34951340, 2022). "NDRG2 expression in breast cancer could reduce PD-L1 expression and restore the T cell proliferation activity suppressed by PD-L1 expression on tumor cells, indicating a possible role of NDRG2 in PD-L1 downregulation." (PMID 34885221, 2021). "Upregulating NDRG2 expression could inhibit endothelial cell proliferation and tumor angiogenesis in breast cancer cells." (PMID 34013046, 2021). "We demonstrated that NDRG2 overexpression inhibits PD-L1 expression in human breast cancer cells." (PMID 34885221, 2021). "NDRG2 expression in breast cancer cells could restore the T cell proliferation activity that is suppressed by PD-L1 expression on tumor cells." (PMID 34885221, 2021). "Our previous study demonstrated that NDRG2 inhibits NF-κB signaling in breast cancer cells." (PMID 34885221, 2021).
breast carcinoma (continued). "In the present study, we demonstrated that PD-L1 expression on breast cancer cells was significantly downregulated by the overexpression of NDRG2, leading to the prevention of tumor cell-induced interference of splenic T cell proliferation stimulated with a combination of anti-CD3/CD28 antibodies." (PMID 34885221, 2021). "Because NDRG2 overexpression affected PD-L1 expression in breast cancer cells, we tested whether NDRG2 downregulation was able to influence PD-L1 expression on tumor cells." (PMID 34885221, 2021). "Upregulating NDRG2 expression inhibited the proliferation and tumor angiogenesis in breast cancer." (PMID 34013046, 2021). "Interestingly, it has been revealed the correlations between cancer (such as lung, prostate, liver, colorectal and breast cancer) and N-myc downstream-regulated gene 2 (NDRG2)." (PMID 32345304, 2020). "Taken together, our data showed that NDRG2 could increase ADR sensitivity in breast cancer MCF-7 cells." (PMID 28423695, 2017). "Also, NDRG2 overexpression can inhibit tumor growth and invasion in vitro in bladder and breast cancer." (PMID 28390436, 2017). "Taken together, we have identified that NDRG2 could increase Bad stability to promote apoptosis of breast cancer cells." (PMID 28423695, 2017). "NDRG2 has been found decreased or null expressed in breast cancer and other tumor tissues." (PMID 28423695, 2017). "Our experiments demonstrated for the first time that tumor suppressor NDRG2 was significantly decreased in MCF-7/ADR cells, and NDRG2 overexpression could improve breast cancer cells sensitivity to ADR." (PMID 28423695, 2017). "In summary, our results demonstrated that NDRG2 could promote chemotherapy sensitivity in breast cancer." (PMID 28423695, 2017). "Likewise, NDRG2-overexpressing breast cancer cells exhibited a reduced level of p-Akt even after stimulation with IGF-1 (Insulin-like growth factor 1)." (PMID 27447861, 2016). "Notably, associations between cancer (including lung cancer, prostate cancer, liver cancer, colorectal cancer and breast cancer) and N-myc downstream-regulated gene 2 (NDRG2) have been reported." (PMID 26506239, 2016). "Our data indicate that the described putative tumor suppressive function of NDRG2 may be confined to luminal- and basal B-type breast cancers." (PMID 27400234, 2016). "Moreover, analyzing distinct gene signatures predicting breast cancer patients’ outcome based on gene expression score values (high vs. low score) indicated a clear clinical significance concerning NDRG2 mRNA expression level." (PMID 27400234, 2016). "Furthermore, in malignant breast cancer cells, NDRG2 overexpression specifically inhibits suppressor of cytokine signaling 1 (SOCS1) phosphorylation and induces the phosphorylation of p38 MAPK." (PMID 26506239, 2016). "NDRG2 overexpression suppresses breast cancer cell adhesion and invasion." (PMID 26506239, 2016). "In addition to the PAM50 intrinsic subtype classification we showed an association of abundant NDRG2 expression to ER-, PR-, and HER2-negative breast cancer specimen of the TCGA data cohort." (PMID 27400234, 2016).
breast carcinoma (continued). "Further observations are needed to confirm the correlation of NDRG2 and breast carcinoma prognosis." (PMID 24636131, 2014). "Targeting the actions of NDRG2 in cell glucose-dependent energy delivery may provide an attractive strategy for therapeutic intervention in human breast carcinoma." (PMID 24636131, 2014). "Furthermore, Kaplan–Meier analysis was used to evaluate the disease-free survival and overall survival of patients with breast cancer and NDRG2 protein expression." (PMID 24636131, 2014). "The effects of NDRG2 on glucose uptake were assessed in breast cancer cells and xenograft tumours." (PMID 24636131, 2014). "Given that the antiproliferative effects of NDRG2 on breast cancer cells were more prominent in high-glucose medium, we investigated whether NDRG2 would affect the capacity of these cells to take in glucose." (PMID 24636131, 2014). "We found that NDRG2 could induce GLUT1 protein degradation to decrease glucose uptake in breast cancer cell lines, but whether this regulatory mechanism also functions in the tumour microenvironment must be studied in vivo." (PMID 24636131, 2014). "In our present study, we tested the hypothesis that a possible mechanism of NDRG2 induces its participation in cancer cell energy metabolism through the regulation of GLUTs in breast carcinoma." (PMID 24636131, 2014). "First, the basic NDRG2 expression in five breast cancer cell lines was examined by immunoblotting." (PMID 24636131, 2014). "We investigated whether NDRG2 is involved in any glucose-dependent energy metabolism, as well as the nature of its correlation with breast carcinoma." (PMID 24636131, 2014). "Moreover, NDRG2 expression negatively regulates JAK2/STAT3 through the regulation of the suppressor of cytokine signaling 1 gene in breast cancer cells." (PMID 25061501, 2014). "The data imply that NDRG2 expression might be involved in the development and progression of breast cancer and that NDRG2 expression is inversely correlated with GLUT1 expression in breast carcinoma." (PMID 24636131, 2014). "This makes it unlikely that Myc acts as a repressor for NDRG2 gene expression in breast cancer." (PMID 21226903, 2011). "Thus, another regulatory pathway than repression by Myc appears to reduce NDRG2 mRNA levels in breast cancer." (PMID 21226903, 2011). "Finally, our results suggest that the observed reduction of NDRG2 mRNA in breast cancer correlated weakly with MYC mRNA expression." (PMID 21226903, 2011). "However, whether NDRG2 is related to miR-181a-5p to participate in the progression of breast cancer was unknown." (PMID 34951340, 2022). "However, the role of NDRG2 in different subtypes of breast cancer is also controversial." (PMID 34951340, 2022). "Furthermore, miR-181a-5p promoted cell proliferation, invasion and glycolysis of breast cancer by targeting NDRG2 via the PTEN/AKT pathway, suggesting that miR-181a-5p may be a potential target for breast cancer therapy." (PMID 34951340, 2022). "In line with this hypothesis, PD-L1 expression in MBA-MB-231 breast cancer cells was significantly influenced by the modulation of NDRG2 expression, and it had a remarkable impact on the proliferation activity of stimulated splenic T cells after coculturing with mouse breast tumor cells." (PMID 34885221, 2021). "In addition to T cell proliferation, a significant negative association between NDRG2 and PD-L1 expression was observed in basal and triple-negative types of human breast cancer tissues through TCGA database analysis." (PMID 34885221, 2021). "To confirm whether the inhibitory effect of NDRG2 overexpression on PD-L1 expression was related to the regulation of STAT3 or NF-κB activation in mouse breast cancer cells, we examined the phosphorylation levels of STAT3 and NF-κB in 4T1-mock and -NDRG2 cells." (PMID 34885221, 2021).
breast carcinoma (continued). "By analyzing the response of ADR-treated breast cancer cells, we found that overexpression of NDRG2 could inhibit proliferation, enhance DNA damage response, and promote apoptosis, all of which suggests the great potential of NDRG2 in increasing drug sensitivity of breast cancer cells." (PMID 28423695, 2017). "Besides the putative estrogen-dependent regulation of NDRG2 in luminal type breast cancer, divergent expression profile of NDRG2 may be due to the metastatic behaviour of basal-like tumors." (PMID 27400234, 2016). "Ectopic expression of NDRG2 inhibits the tumor growth through inducing suppressor of cytokine signaling 1 and subsequent inactivation of signal transducer and activator of transcription 3 in breast cancer cells or by attenuating the AP-1 activity in colon carcinoma cells." (PMID 25889839, 2015). "In addition, NDRG2 suppresses the proliferation of breast cancer cells by reducing VEGF expression." (PMID 25889839, 2015). "NDRG2 may be viewed as an attractive therapeutic target for breast carcinoma." (PMID 24636131, 2014). "In addition, a previous study reported that NDRG2 could inhibit the metastatic potential of breast cancer cells, specifically via the suppression of CD24 or MMP-9 expression." (PMID 23800335, 2013). "NDRG2 has been described mostly as a tumor suppressor, and more information is needed regarding the functions of NDRG3 and NDRG4 in breast cancer." (PMID 38611020, 2024). "The expression of NDRG2 is downregulated in various cancers, including adult T-cell leukemia-lymphoma (ATLL), breast cancer, prostate cancer, lung cancer, and thyroid cancer." (PMID 37958443, 2023). "The analysis of the TCGA dataset also showed that the expression of NDRG2 and EHF in breast cancer patients was positively correlated in the basal subtype." (PMID 37958443, 2023). "However, the role of EHF in breast cancer and its relationship with NDRG2 remain unknown." (PMID 37958443, 2023). "NDRG2 overexpression enhanced the proapoptotic effect and attenuated AMPK phosphorylation induced by glucose deprivation in a breast cancer cell, MDA-MB231." (PMID 34685629, 2021). "Here, we explored the role of NDRG2 in chemo-resistance with a focus on Adriamycin (ADR) and found that NDRG2 expression decreased in ADR resistance breast cancer cells." (PMID 28423695, 2017). "NDRG2 interacts with and degrades GLUT1 through the proteasome, thereby decreasing glucose uptake in breast cancer cells." (PMID 27447861, 2016). "Consistent with the cell- and animal-based results, a significantly inverse correlation between NDRG2 and GLUT1 expression was observed in clinical breast cancer tissue specimens." (PMID 24636131, 2014). "In our present study, we first investigated this relationship between NDRG2 and GLUT1 expression by IHC and immunoblotting in 30 pairs of breast carcinoma and adjacent normal breast tissue specimens." (PMID 24636131, 2014). "The correlations between NDRG2 expression and glucose transporter 1 (GLUT1) expression in clinical breast carcinoma tissues were analysed." (PMID 24636131, 2014). "In that previous study, we detected that NDRG2 bound to and partly colocalised with GLUT1 in the cytoplasmic region of breast cancer cells." (PMID 24636131, 2014). "We further evaluated the effects of iron chelators on NDRG2, 3, and 4 expressions in breast cancer cells as these members have not been studied as extensively as NDRG1 in the context of carcinogenesis." (PMID 38983911, 2024).